BRAF (B-Raf proto-oncogene, serine/threonine kinase)
Diseases named in the same sentence as BRAF in open-access papers (continued):
Sharing a sentence is not in itself a finding about the gene and the disease.
melanoma (continued). "This is consistent with recent reports that show BRAFi treatment induces degradation of HIF-1α at both mRNA and protein levels in drug-tolerant BRAF-mutated melanoma cells." (PMID 32923395, 2020). "While the prognostic significance of BRAF/NRAS mutations in melanoma is still debated, numerous studies reported that TERTprom mutations associate with poor prognosis." (PMID 32290374, 2020). "Based on the results of the phase-III clinical trial IMspire 150, the FDA approved the use of the latter triple combination for advanced-stage melanoma patients harboring BRAF exon 15 p.V600 point mutations." (PMID 33260892, 2020). "For example, ERK inhibitors are active against cancers harbouring diverse BRAF-mutations, as well as melanomas with BRAF–MEK inhibitor resistance." (PMID 31819183, 2020). "Although an heterogenous pattern in term of gene expression levels was clearly displayed among patients, deregulation of the miR-146a/COX2 axis occurs in a subset of melanoma patients and is associated with the development of BRAF/MEKi drug resistance." (PMID 32967672, 2020). "Regardless of the underlying molecular mechanism, induction of Gal‐1 in BRAF inhibitor‐treated, progressing melanoma patients is an important observation from the translational standpoint." (PMID 32330348, 2020). "Approximately 50% of melanomas harbour activating BRAF mutations and over 90% of these give rise to the mutant protein BRAFV600E." (PMID 31819183, 2020). "BRAF inhibitors (BRAFi) have shown remarkable clinical efficacy in the treatment of melanoma with BRAF mutation." (PMID 32532957, 2020). "In this context, unprecedented responses have been observed in BRAF mutated melanoma after treatment with BRAF V600E targeted therapy." (PMID 32098410, 2020). "Of the melanomas with BRAF gene mutations, 15% (5/32) had a thickness less than 1 mm, 12.5% (4/32) a thickness between 1 and 2 mm, inclusive, 9.3% (3/32) a thickness greater than 2 mm up to 4 mm, and 21.8% (7/32) a thickness greater than 4 mm." (PMID 32775409, 2020). "A frequent TERT promoter polymorphism at −245 was associated with an increased rate of metastasis in melanoma and inversely correlated with BRAF mutation." (PMID 32850962, 2020). "For instance, patients with lung cancer, colon cancer, or melanoma bearing BRAF V600E mutations all benefit from inhibitors targeting this mutation." (PMID 33425905, 2020). "Around half of melanoma carry a mutation in the BRAF gene, which results in the dysregulation of several molecular signaling pathways." (PMID 32178401, 2020). "By activating the MAPK cascade, the BRAF(V600E) mutation stimulates melanoma cells to produce a wide spectrum of chemokines and cytokines which, in turn, are responsible for the recruitment of immune and myeloid cells." (PMID 32604720, 2020). "Providing further relevance for visfatin in the progression of melanoma, its elevated levels were found in the serum of patients with BRAF-mutated metastatic melanoma with decreasing concentrations in response to BRAF/MEK inhibitor therapy." (PMID 33260746, 2020). "Melanoma frequently harbors the BRAF p.Val600Glu mutation, which is also commonly found in benign nevi." (PMID 32847629, 2020). "Considering that this hotspot of KRAS has more clinical significance than that of the rare mutation in BRAF based on the knowledge at present, this melanoma was classed into the RAS group." (PMID 32083130, 2020). "Interplay between the CDKN2 proteins and other key drivers of melanoma progression such as BRAF and NRAS mutations must be required for centrosome overduplication." (PMID 32067956, 2020).
melanoma (continued). "This is exemplified by the assessment, in melanoma tissue samples, of the expression of BRAF mutations, which is currently the most robust predictive biomarker influencing eligibility to targeted therapy with vemurafenib and dabrafenib." (PMID 32659961, 2020). "The frequency of BRAF mutations in multiple cancer types and especially melanoma motivates the development of small molecules targeting mutant BRAF." (PMID 32413516, 2020). "Mutational load of BRAF V600E was analyzed by digital PCR in 78 biopsies of melanoma patients of different stages and 10 nevi." (PMID 32168325, 2020). "It was just recently described that long-term vemurafenib treatment in BRAF-mutant melanoma cells can lead to increased migration in association with elevated EGFR expression." (PMID 32613561, 2020). "BRAF inhibitors are targeting the most prevalent melanoma-driving mutation, BRAFV600E and several molecules in this category are FDA approved (NIH U. S. National Library of Medicine, 2019)." (PMID 32266211, 2020). "The diversity of genetic changes driving resistance, and the inter- and intra-individual heterogeneity of resistance-associated mutations complicates treatment of BRAF inhibitor-resistant melanoma." (PMID 33003483, 2020). "In summary, we isolated EVs from melanoma cell lines carrying either the BRAF V600E or an NRAS mutation under normoxia and hypoxia." (PMID 32183388, 2020). "Specific therapeutic targeting of BRAF V600E with mutation specific BRAF inhibitors in combination with MEK inhibitors is effective in melanomas with this molecular background." (PMID 32131760, 2020). "In melanoma, BRAF mutations are found in approximately 50% of stage IV disease, and of those roughly 70% are V600E and 20% are V600K." (PMID 33042847, 2020). "Prolonged BRAF inhibitor treatment for melanoma xenografts carrying BRAF activation mutations leads to resistance." (PMID 33299637, 2020). "BRAF is a serine/threonine kinase that harbors activating mutations in ∼7% of human malignancies and ∼60% of melanomas." (PMID 32413516, 2020). "Most mutations in melanoma affect one critical amino acid on BRAF gene, resulting in the V600E substitution." (PMID 32393282, 2020). "In general, MAP2K1/2 mutations in BRAF V600E melanomas are linked to both intrinsic and acquired resistance to BRAF inhibitors." (PMID 32850962, 2020). "Among these driver genes, BRAF is the most important in a clinical setting because BRAF/MEK inhibitors can be used for the treatment of BRAF-mutated melanoma." (PMID 32143442, 2020). "BRAF mutations are associated with poorer survival in patients with melanoma, but the significance of BRAF mutations among NPC patients has not been thoroughly investigated." (PMID 31664962, 2019). "BRAF mutations are present above all in melanomas, papillary thyroid carcinomas and colorectal cancers." (PMID 31126017, 2019). "When taken together, these results demonstrate that lncRNA IGF2AS, antiPeg11, MEG3, and Zeb2NAT appear to be independent prognostic factors in BRAF-mutated advanced melanoma patients treated with vemurafenib." (PMID 31231466, 2019). "In melanoma, BRAF mutation frequency varies on the basis of the histologic subtype, the anatomical location of the tumor, and the sun exposure pattern." (PMID 30934534, 2019). "We decided to follow a non-invasive approach directed to analyse by immunofluorescence the phosphorylation status of the ErbB3 receptor in CTCs isolated from BRAF mutated melanoma patients before the initiation of therapy and 3 days after the start of therapy." (PMID 31557826, 2019). "In this regard, the BRAF V600E protein mutation was found to be associated with several immune-related alterations, examples of which are available both in melanoma and in differentiated thyroid cancer." (PMID 31762942, 2019). "In spite of having an unrelated chemical structure, binimetinib (MektoviTM) and encorafenib (BraftoviTM) were approved for the treatment of BRAF-mutated melanoma." (PMID 30813407, 2019).
melanoma (continued). "In pair 18, a biopsy specimen taken from the left lower lip showed malignant melanoma with a mitosis rate at 10/mm2 and a BRAF p.V600E mutation at 11% VAF, consistent with an estimated tumor cellularity at 20–40%." (PMID 31277584, 2019). "BRAF mutations have been associated with various cancers, somatic missense mutations appearing in 66% of malignant melanomas." (PMID 30935124, 2019). "NRAS is second in the percentage of recurrently mutated genes in melanoma and accounts for close to 30% of mutated melanomas in a mutually exclusive way with BRAF." (PMID 30987166, 2019). "About half melanoma patients carry a BRAF mutation and are typically given combined BRAF and MEK inhibitors such as dabrafenib and trametinib, vemurafenib and cobimetinib, and encorafenib and binimetinib (FDA-approved)." (PMID 31118886, 2019). "BRAF mutation associates with anoikis resistance in melanoma cell lines and in HT29 intestinal cancer cells." (PMID 31545494, 2019). "Constitutively active mutated BRAF kinase occurs in more than 40% of patients suffering from melanoma." (PMID 31877948, 2019). "The pathogenic variants detected in the pre-treatment scalp melanoma included the BRAF-V600E mutation (BRAF c.1799 T > A, p.V600E), amplification of BRAF located on chromosome 7q34, and loss of the tumor suppressor gene CDKN2A located on chromosome 9p21.3." (PMID 31703593, 2019). "Similar to KRAS, BRAF is a well-known proto-oncogene and the p.V600E mutation is implicated in a number of cancers including melanoma, colorectal carcinoma, and papillary thyroid carcinoma." (PMID 31891627, 2019). "BRAF gene mutations are commonly associated with a more aggressive behaviour of melanoma or thyroid cancer." (PMID 31762942, 2019). "Mutations of NRAS, an upstream effector of BRAF, were found in 20% of melanoma patients and are considered to be mutually exclusive with BRAF mutations." (PMID 31877948, 2019). "A weak association between specific mutations or total number of mutations with either measure of efficacy was shown among patients with either BRAF- or NRAS-mutated melanoma (respectively)." (PMID 30956763, 2019). "Kinase inhibitors (KIs) of the MAPK pathway were developed following the discovery that BRAF mutations occurring in nearly 50% of patients are major oncogenic drivers of melanoma proliferation and survival." (PMID 30254376, 2019). "Previous studies, prior to the recent categorization of 3 classes of BRAF mutation, have shown impact of non-V600 BRAF mutations on disease characteristics and clinical outcomes in melanomas and colorectal cancers." (PMID 31277584, 2019). "Targeted therapy against melanoma performed with dabrafenib or vemurafenib BRAFi in patients that harbor BRAF mutations is initially effective but subsequently fails because alternative tumor-growth-inducing pathways are activated." (PMID 31783660, 2019). "BRAF-mutated melanomas are frequently treated with vemurafenib, a targeted therapy to inhibit the oncogenic BRAF pathway." (PMID 31316083, 2019). "We can conclude that there is a clear radiosensitizing effect of BRAF inhibitors in BRAF-mutated melanoma cells, and these data are supported by other reports." (PMID 31374895, 2019). "In this paper, the study was designed to find potential genes and correlated pathways associated with the expression level and mutation status of BRAF in melanoma samples." (PMID 30925905, 2019). "One of the most relevant targeted proteins is BRAF, a Ser/Thr protein kinase mutated in 60–70% of melanoma patients, mostly as a V600E substitution." (PMID 31115969, 2019). "No patients had a complete response, and 6 of 30 patients (20%) with NRAS-mutated melanoma (3 confirmed) and 8 of 41 patients (20%) with BRAF-mutated melanoma (2 confirmed) had a partial response." (PMID 30956763, 2019).
melanoma (continued). "In melanoma, more than 20 BRAF mutations have been described; among them, the BRAFV600E mutation is the most prevalent, accounting for 80–90% of all BRAF mutations in melanomas and being present in almost 60% of all cutaneous melanomas." (PMID 30934534, 2019). "A secondary BRAF resistant mutation was also detected in metastatic BRAF mutant melanoma using detailed imaging studies and genetic analyses." (PMID 31126017, 2019). "Specifically, as an MAPK inhibitor, we selected vemurafenib, since it represents a standard melanoma first‐line treatment in BRAF‐mutated melanoma." (PMID 31115969, 2019). "Patient-derived NRAS mutated (BAK and BUL) and BRAF mutated (STU) melanoma cell lines were exposed to increasing concentrations of the MEK1/2 inhibitor trametinib (T), MBZ or a combination of T + MBZ." (PMID 31480477, 2019). "The aim of this study was to explore the molecular differences between melanoma tumor subtypes, based on BRAF and NRAS mutational status." (PMID 31076580, 2019). "EGFR mutational analysis in lung cancer, KRAS in colorectal cancer and BRAF in melanoma all represent examples of mutational tests that are routinely performed on appropriate patients with these cancers." (PMID 31632973, 2019). "BRAF inhibition is associated with increased melanoma antigen expression, including Melan-A and TYRP2 (DCT)." (PMID 31354817, 2019). "The combination of dabrafenib plus trametinib is a standard treatment for patients with BRAF-mutated melanoma." (PMID 31284513, 2019). "While oncogenes have been shown to induce senescence in primary cells, NRAS* and BRAF*-mutated melanoma cells have theoretically negotiated this checkpoint to attain a malignant and immortal state." (PMID 30651601, 2019). "Previous melanoma studies report that BRAF V600 mutations were found approximately twice more often in the trunk compared to non-trunk locations." (PMID 31890008, 2019). "For example, MEK inhibitors and inhibitors of the PD-L1/PD1 axis are often used sequentially in the treatment of BRAF V600E mutated melanoma and are under investigation in combination." (PMID 31671149, 2019). "The mutually exclusivity between loss-of-function mutations in NF1 and oncogenic mutations in RAS and BRAF is also observed in melanoma patients (TCGA)." (PMID 30858928, 2019). "Vemurafenib and dabrafenib were the first and second FDA (Food and Drug Administration) approved targeted therapies for BRAF-mutated melanomas, respectively, and then combination therapies of BRAF and MEK inhibitors became available." (PMID 30866509, 2019). "About 50% of melanoma patients harbor activating mutations in BRAF with BRAFV600E as the main protein product, whereas NRAS is mutated in about 15–20% of cases." (PMID 31167513, 2019). "For instance, we identified an activating and putative resistance NRAS mutation (Q22K) in both gDNA and ctDNA in a BRAF-mutant melanoma after progression on combined BRAF and MEK inhibitors." (PMID 31795494, 2019). "As a result, combination therapy with MEK inhibitors (such as trametinib) and class 1 BRAF inhibitors (such as dabrafenib) have become FDA-approved standard of care for patients with metastatic BRAF-mutated melanomas." (PMID 31581557, 2019). "In late stage prostate tumors, EZH2 upregulation is related to gene amplification, whereas its expression is profoundly affected by the BRAF (V600E) mutation in melanoma." (PMID 31921860, 2019). "Although some driver mutations in BRAF or NRAS genes have been identified in melanoma, the efficiencies of their inhibitors are still limited." (PMID 31231466, 2019).
melanoma (continued). "Targeted treatment of metastatic melanoma using small molecule inhibitors directed against mutated BRAF kinase or downstream kinases such as MEK1/2 is currently a mainstay of melanoma therapy." (PMID 30987166, 2019). "Here we show that in vitro Lmat-LLO causes ROS production and, in turn, apoptotic killing of a wide variety of melanoma cells, irrespectively of their stage, mutational status, sensitivity to BRAF inhibitors or degree of stemness." (PMID 30664692, 2019). "In most previous studies, a correlation between BRAF-mutation and shorter OS has been restricted to advanced metastatic disease, while the results in early stage melanomas have been conflicting." (PMID 31039200, 2019). "Genetic mechanisms of resistance apply to BRAF alone: amplification of gene copying and alternative splicing, which were detected in 20%–32% of melanoma cases, or genes encoding proteins directly, and indirectly interacting with BRAF kinase." (PMID 31877948, 2019). "In melanoma, for example, up to 70% of these tumors have point mutations in the BRAF gene, the majority of which lead to a single amino acid substitution of valine for glutamic acid at position 600 (the BRAFV600E mutation)." (PMID 30487597, 2019). "Firstly, we have identified overlapping genes associated with the expression and the mutation status of BRAF in melanoma through WGCNA and DEGs analysis, respectively." (PMID 30925905, 2019). "In a BRAF-mutated model of mouse melanoma, the BRAF-inhibitor PLX4720 selectively decreased the number of CD4+Foxp3+ Treg cells and of CD11b+Gr1+ myeloid-derived suppressor cells (MDSC) in the tumor microenvironment." (PMID 31762942, 2019). "Six patients with both CM and PTC were tested, of which 4 were found to be positive for BRAF V600E mutation in melanoma, 6 for BRAF V600E in PTC and 4 in both." (PMID 31164959, 2019). "Approximately 50% of melanomas have a mutation in BRAF which results in the constitutive activation of the Ras/Raf/MEK pathway." (PMID 30701196, 2019). "Studies of the use of combination therapy in adult BRAF mutated melanoma have demonstrated a decreased incidence of cutaneous side effects when compared to BRAF inhibitor monotherapy." (PMID 30728904, 2019). "The most common reasons for non-participation were patients declining to participate (85 patients), melanoma with BRAF mutation (33 patients), evidence of brain metastases (33 patients), and uncontrolled co-morbidities (15 patients)." (PMID 30428063, 2019). "In this cohort of patients with metastatic BRAF V600 mutated melanoma, median OS for patients treated with front‐line niv/ipi or aPD‐1 was NR and 39.5 months." (PMID 31677253, 2019). "Vemurafenib, a BRAF V600E inhibitor, was tested in a basket study of non-melanoma BRAF V600 mutated cancers." (PMID 31277524, 2019). "Up to 50% of all advanced melanoma patients harbor BRAF mutations, making it a good target for BRAF inhibitors." (PMID 30886831, 2019). "Some of the biomarkers for target therapy are frequent events in particular tumor types (eg RAS mutations in colorectal cancer or BRAF mutations in melanoma)." (PMID 31857850, 2019). "We recently reported on the thrombophilic status of BRAFv600 mutated melanoma patients upon BRAF inhibitors and showed that high d-dimer levels correlate with poor overall response rate, progression free survival and overall survival." (PMID 31467489, 2019). "The secondary acquisition of an NRAS* mutation in a BRAF* melanoma cell has also been described in the context of therapeutic resistance." (PMID 30651601, 2019). "In melanoma cells harboring the low-activity BRAF mutations (D594G or G469E), targeting CRAF with either sorafenib or small interfering RNAs decreases ERK phosphorylation and induces apoptosis." (PMID 31398831, 2019).